GSN (gelsolin)
Diseases named in the same sentence as GSN in open-access papers (continued):
Sharing a sentence is not in itself a finding about the gene and the disease.
breast carcinoma (31 papers, 2006 to 2024). "This study examined GSN expression and its diagnostic and predictive significance in pan-cancer and used the serum of breast cancer patients to verify it." (PMID 37035750, 2023). "Overexpression of Gelsolin gene is a leading cause of axillary lymph node metastasis in patients with breast cancer." (PMID 33391377, 2021). "They found that the expression level of the Gelsolin gene was down-regulated in breast cancer tissues and was associated with metastatic growth as well as death in breast cancer cases." (PMID 33391377, 2021). "Downregulation of gelsolin is reported in breast cancer patients harboring a BRAC1 mutation and those receiving doxorubicin chemotherapy." (PMID 34947825, 2021). "Accordingly, association of plasma gelsolin levels with BRCA1 mutation status increased the sensitivity of this combined biomarker in early diagnosis of breast cancer." (PMID 30149613, 2018). "Evidence indicated that GSN gene loss is one of the most common disorders in invasive and metastatic breast cancers." (PMID 26482896, 2015). "Our results suggested that TGF-β1 acting by epigenetic modulation of GSN gene expression might be linked to the signalling events for breast cancer stem cell differentiation." (PMID 26482896, 2015). "Clearly, the upregulation of GSN could alter the cell surface adhesion associated with morphological modification in breast cancer cells." (PMID 26482896, 2015). "An inverse association between gelsolin expression and patient survival time has been observed in lung cancer and breast cancer, suggesting cellular motility mediated through gelsolin expression plays an important role in the progression and prognosis of malignant tumors." (PMID 16882345, 2006). "Importantly, elevated levels of gelsolin expression have been detected in human non-small cell lung, colorectal, and pancreatic carcinomas and depletion of gelsolin using siRNAs in pancreatic, prostate, colorectal, and breast carcinoma cell lines caused a marked reduction in cell motility." (PMID 27724924, 2016). "For example, Mbd2 deletion decreased the expression of Gsn (encoding Gelsolin), a protein involved in TGF-β-mediated induction of EMT in breast cancer." (PMID 38556549, 2024). "Previous studies have shown that decreased GSN expression enhanced mesenchymal marker expression to promote cell migration, invasion, and metastasis in several types of cancers such as breast cancer, glioblastoma, and gastric cancer." (PMID 38175202, 2024). "Gelsolin (GSN) is a multifunctional actin-binding protein that is greatly decreased in many transformed cell lines in tumor tissues, including breast cancers." (PMID 39061201, 2024). "GSN expression was significantly lower in breast carcinoma, cervical carcinoma, colorectal adenocarcinoma and uterine carcinoma compared with the corresponding normal tissues." (PMID 37958747, 2023). "In breast cancer, GSN downregulation was triggered via hypermethylation of essential DNA methylation sites." (PMID 37035750, 2023). "The histone deacetylase inhibitor trichostatin A increases GSN expression in the breast cancer cell lines MDA231, MCF7, and T47D." (PMID 36291171, 2022). "Our study also found that CAV2 and GSN were down-regulated in breast cancer, which is consistent with the results of previous studies." (PMID 35178391, 2022). "In other words, Gelsolin gene expression was lower in the breast cancer group compared to control group and mismatching our findings, the level was even lower in patients with metastatic involvements." (PMID 33391377, 2021). "Our results reveal that Gelsolin gene expression is significantly higher in breast cancer cases with axillary lymph node metastasis which highlights greater stages of the disease in these cases." (PMID 33391377, 2021). "This study mainly aims to determine the relationship between Gelsolin and Villin genes expression and metastasis of axillary lymph nodes in patients with breast cancer." (PMID 33391377, 2021).
breast carcinoma (continued). "Overexpression of gelsolin in breast cancer patients was directly proportional to cancer stage and resulted in increased metastasis to lymph node." (PMID 33171868, 2020). "In colon cancer, for instance, overexpression of GSN reduces proliferation and invasion of colon carcinoma cells and in breast cancer downregulation of GSN correlates with malignant progression." (PMID 33014872, 2020). "GSN overexpression has been seen in many cancers, including breast cancer, oral carcinoma cells, colorectal cancer, ovarian cancer, and leukemia." (PMID 31001458, 2019). "Silencing of EGR-1 with syntactic catalytic DNA has been reported to inhibit human breast carcinoma proliferation and migration, while on the other hand downregulation of gelsolin (indicator of breast cancer) has been correlated with suppression of EGR-1." (PMID 28758926, 2017). "To further determine the functional role of increased GSN expression in the TGF-β induced signaling for modulation of breast cancer cell progression, we conducted GSN overexpression (GSN op) in the two human breast cancer cell lines of MDA-MB231 and MCF-7." (PMID 26482896, 2015). "Decreased GSN expression has been found in many transformed and malignant cancer cells, including breast cancers." (PMID 26482896, 2015). "GSN is down-regulated in human breast cancer tissues compared to controls and its transcript level is linked with metastasis development and death." (PMID 24748173, 2014). "Studies have shown that GSN gene transcription is down-regulated in breast cancer of humans and some animals, and the activation of GSN may be a protective factor in the treatment of cancer cells against cancer." (PMID 35178391, 2022). "In summary, our research has found two key genes (CAV2 and GSN) related to breast cancer that may be regulated by DNA methylation and discovered three DNA methylation probes (cg13569051, cg14399183, and cg25274503)." (PMID 35178391, 2022). "Gelsolin promoter was less active in low-gelsolin-expressing breast cancer cells." (PMID 33171868, 2020). "Also the observation that downregulation of GSN in breast cancer promoted malignant transformation agrees with our study." (PMID 33014872, 2020). "Evidences suggest that GSN may act as a tumor suppressor gene, indeed, several studies showed a GSN down-regulation in human cancers including breast carcinoma." (PMID 30925779, 2019). "Considering the reports indicating pro-tumorigenic activity of gelsolin in breast cancers and its implication in inflammation, its reduction in plasma samples suggests reduced invasiveness of cancer and might predict response to neoadjuvant chemotherapy." (PMID 30149613, 2018). "This is consistent with our previous finding that both GSN and Tm1 could affect the cell surface adhesion and cell proliferation in breast cancer cells." (PMID 26482896, 2015). "Alterations in GSN RNA expression in most breast cancers of rats, mice, and humans have been shown not due to gross mutations of the GSN gene." (PMID 26482896, 2015). "However, it remains to be determined if the TGF-β signaling events also include the modulation of GSN expression for promotion of breast cancer cell differentiation." (PMID 26482896, 2015). "In addition, we also verified that GSN plays a role in the gene expression for the mesenchymal cell marker, vimentin in breast cancer cells with GSN op and/or siGSN approaches." (PMID 26482896, 2015). "Further analyses, performed using a panel of breast cancer cell lines, allowed us to further elucidate the signaling network that might modulate the expression of gelsolin in breast cancer." (PMID 26061043, 2015). "To test whether GSN plays a role in controlling cell proliferation and motility, we conducted GSN overexpression (GSN op) in the two human breast cancer cell lines of MDA-MB231 and MCF-7." (PMID 26482896, 2015).
breast carcinoma (continued). "This suggested that GSN severing the actin filament might contribute to offset the cell adhesion and or detachment to extra-cellular matrices in breast cancer cells." (PMID 26482896, 2015). "The results revealed a notable downregulation of AVPR1A, FEZ1, HGF, GSN, NEDD9, and EGR3 expression in the breast cancer cell lines (MCF7, BT-474, SK-BR-3, MDA-MB-231) when compared to the normal mammary epithelial cell line (MCF-10A)." (PMID 38756447, 2024). "The authors concluded that TGF-β1 promoted the demethylation of the GSN gene promoter in these cells, inducing epigenetic modifications that contributed to the progression of EMT in breast cancer cells." (PMID 39061201, 2024). "Gelsolin, Protein Daple, Heat shock protein HSP 90-beta, Alpha-1-antitrypsin, and Cathepsin D constitute serum biomarker signature for diagnosing early grade breast cancer." (PMID 31945087, 2020). "TGF-β1 acted on MDA-MB231 breast cancer cells by decreasing cell proliferation, changing cell morphology to a fibroblast-like shape, increasing expressions for CD44 and GSN, and increasing EMT expression and cell migration/invasion." (PMID 26482896, 2015). "Similarly, GSN, upregulated expression in non-small cell lung cancer (NSCLC) and breast cancer tissues, can mediate EMT action to increase cancer cell aggressiveness." (PMID 37035750, 2023). "Similarly, GSN overexpression in squamous cell carcinoma cell line, Tca8113 and TNF-resistant MCF-7 breast cancer cells have been shown sensitize their responsiveness to treatment." (PMID 36291171, 2022). "Four of the top 20 genes are upregulated in cancer stem cells, including Id3 in cancer stem cells of a mouse mammary tumor model and ID3 in intrahepatic cholangiocarcinoma tumors; MGST1 in human pancreatic cancer stem cells; and GPX3 and GSN in quiescent colon cancer stem cells." (PMID 36142331, 2022). "Villin and Gelsolin genes expression were significantly higher in female breast cancer patients with axillary lymph node metastasis in comparison with breast cancer patients who did not deal with such involvement." (PMID 33391377, 2021). "The results of this study were indicative of significantly higher levels of Villin and Gelsolin genes expressions in breast cancer patients with axillary lymph node metastasis rather than cases without axillary lymph node metastasis." (PMID 33391377, 2021). "Taken together, the present study suggested that the modification of GSN expression might involve in the TGF-β1 signaling events for inducing cancer cell stemness and increasing cell migration and invasion in CD44+/CD24- subpopulation of breast cancer cells." (PMID 26482896, 2015). "However, the relationship between the expression level of GSN and the TGF-β signaling for EMT progression in breast cancer cells is not clear." (PMID 26482896, 2015). "However, in previous studies on breast cancer, there was almost no discovery of the relationship between the DNA methylation of cg25274503 and CAV2 expression and the DNA methylation of cg13569051 and cg14399183 and the GSN expression." (PMID 35178391, 2022).
ovarian carcinoma (24 papers, 2018 to 2025). A malignant neoplasm originating from the surface ovarian epithelium. "Increased levels of plasma gelsolin in ovarian cancer tissues are associated with a poorer clinical prognosis." (PMID 39942602, 2025). "The elevated expression of plasma gelsolin was associated with chemoresistance and poorer overall survival of patients with ovarian cancer." (PMID 36766698, 2023). "For instance, exosome actin-associated protein cytosolic gelsolin transforms chemo-sensitive ovarian cancer cells into resistant counterparts through both autocrine and paracrine mechanisms." (PMID 37957701, 2023). "They reported higher Gelsolin gene expression in women with ovarian cancer which was associated with more tumor growth and poorer clinical prognosis." (PMID 33391377, 2021). "Plasma gelsolin, a plasma clotting protein, promoted resistance in ovarian cancer cells following exosomes transport." (PMID 39942602, 2025). "Levels of plasma gelsolin that is released through exosomes are increased in chemoresistant ovarian cancer cells compared with those of chemosensitive cells." (PMID 38796525, 2024). "This correlates with poor overall survival and relapse-free survival in ovarian cancer patients and shows that the exosomal transfer of plasma gelsolin is a marker for chemoresistance in ovarian cancer cells." (PMID 38796525, 2024). "Plasma gelsolin (pGSN) overexpression in ovarian cancer (OVCA) disarms immune function, contributing to chemoresistance." (PMID 38891037, 2024). "Serum GSN levels are significantly reduced in patients with ovarian cancer compared with healthy patients and have been shown to be a crucial factor in regulating chemoresistance in vitro." (PMID 37046833, 2023). "Plasma gelsolin was shown to be transferred via exosomes to chemosensitive ovarian cancer cells conferring cisplatin resistance." (PMID 36766698, 2023). "Although the over-expression of plasma gelsolin (pGSN) protects ovarian cancer cells from chemotherapy-induced death, its immunological role in the tumor microenvironment is less explored." (PMID 35205790, 2022). "Exosomal plasma gelsolin enhanced the survival of ovarian cancer cells via both autocrine and paracrine mechanisms to enhance chemoresistance." (PMID 35024437, 2022). "The enhanced expression of exosome-carried plasma gelsolin from ovarian cancer cells weakened the immunosurveillance and promoted the synthesis of glutathione, which subsequently caused chemoresistance in ovarian cancer." (PMID 35024437, 2022). "The expression of gelsolin in ovarian cancer tissues and cell lines revealed considerably low levels of GSN, in contrast to its expression in the epithelium of normal ovaries and benign adenomas." (PMID 30149613, 2018). "Additionally, higher plasma gelsolin (pGSN) expression was observed in chemotherapy-resistant ovarian cancer cells compared to sensitive ones." (PMID 39334866, 2024). "In addition, the expression and secretion of GSN were higher in chemoresistant ovarian cancer cells than in chemosensitive ovarian cancer cells." (PMID 36669591, 2023). "Zhang and colleagues identified LBP (lipopolysaccharide-binding protein), GSN (gelsolin), FGA (fibrinogen alpha chain), and FGG (fibrinogen gamma chain) as potential diagnostic exosomal proteins for ovarian cancer, with FGA found to be the most promising diagnostic marker." (PMID 34571921, 2021). "Furthermore, a reduced serum level of gelsolin is well-documented in ovarian cancer." (PMID 34947825, 2021). "Cisplatin-resistant ovarian cancer cells secrete exosomes carrying plasma gelsolin (pGSN), which induce CD8(+) T lymphocyte apoptosis, decrease IFN-γ secretion, and increase the glutathione (GSH) content in ovarian cancer cells, enhancing immune resistance." (PMID 39334866, 2024). "Plasma GSN is a well-known poor prognostic biomarker for PFS and OS in patients with ovarian cancer." (PMID 36669591, 2023).
ovarian carcinoma (continued). "GSN is an actin-binding protein downregulated in CC, HCC, GC, cervical cancer, ovarian cancer, and BC." (PMID 37834160, 2023). "Importantly, the serum expression level of gelsolin was significantly decreased in the HGSOC cohort of patients when compared to the control group, which could considerably improve the diagnostic possibilities in ovarian cancer patients." (PMID 30149613, 2018).
bladder cancer (20 papers, 2009 to 2025). "In conclusion, the current study indicates that GSN expression is associated with bladder cancer proliferation, migration and enhanced cell apoptosis through inhibition of the expression of NF-κB." (PMID 37958747, 2023). "Here, we sought to investigate the functional significance and the underlying mechanism of GSN in bladder cancer." (PMID 37958747, 2023). "The data indicated that GSN expression is associated with bladder cancer proliferation, migration and enhanced cell apoptosis through regulation of NF-κB expression." (PMID 37958747, 2023). "For instance, GSN expression is downregulated in human bladder cancer, where its overexpression can actually reduce tumorigenicity." (PMID 39964147, 2025). "Taken together, these data suggest that inhibiting GSN expression decreases cell viability by triggering apoptosis of bladder cancer cells." (PMID 37958747, 2023). "We first assessed the expression level of GSN in a panel of multiple bladder cancer cell lines including 5637, EJ, T24 and SW780 using Western blotting analysis." (PMID 37958747, 2023). "The results showed that GSN is significantly downregulated in bladder cancer compared with normal tissue." (PMID 37958747, 2023). "Higher GSN expression was related to worse outcomes in bladder cancer patients, colorectal cancer, LAML, and LGG (Cox p < 0.05)." (PMID 37035750, 2023). "In order to investigate the downstream signaling pathways that mediate bladder cancer in GSN knockdown, we examined the effect of GSN downregulation on NF-κB p65 expression." (PMID 37958747, 2023). "Although the link between GSN expression level and cancer progression has been suggested, the molecular mechanisms governing its role are not well understood in bladder cancer." (PMID 37958747, 2023). "In order to develop a comprehensive overview of the role of GSN in bladder cancer, a functional characterization was carried out." (PMID 37958747, 2023). "In our previous study, we reported a decrease in GSN expression in bladder cancer using proteomic analysis." (PMID 37958747, 2023). "Our data demonstrated that OD in siGSN#1 treated cells was significantly lower compared with siRNA-treated control cells (p < 0.001), indicating that depletion of GSN is accompanied by a reduction in the proliferation potential of bladder cancer cells." (PMID 37958747, 2023). "The involvement of GSN in the neoplastic transformation of bladder cancer through proliferation, migration and apoptosis was previously reported." (PMID 37958747, 2023). "In the present study, we aimed to further characterize the functional significance of GSN and delineate its regulatory network in bladder cancer." (PMID 37958747, 2023). "Here, we sought to reveal the functional significance of GSN in bladder cancer by undertaking a comprehensive bioinformatic analysis of TCGA datasets and through the assessment of multiple biological functions." (PMID 37958747, 2023). "Simultaneously, we found that knocking down GSN expression reduces proliferation and increases apoptosis of bladder cancer cells in MTS assay and annexin-V assay, respectively." (PMID 37958747, 2023). "Our present study demonstrates, for the first time, that decreased expression of GSN leads to a diminished expression of NF-κB in human bladder cancer cells, T24." (PMID 37958747, 2023). "The involvement of the actin-regulatory protein, gelsolin (GSN), in neoplastic transformation has been reported in different cancers including bladder cancer." (PMID 37958747, 2023). "The expression of GSN in bladder cancer is higher than that in normal tissues, and the prognosis of bladder cancer patients whose gene expression of GSN is up-regulated is worse." (PMID 35178391, 2022). "GSN mediating the level of the actin remodeling can induce the ATGF3 inhibiting the metastasis of bladder cancer cells." (PMID 32640634, 2020).